PINK1 (PTEN induced kinase 1)
Diseases named in the same sentence as PINK1 in open-access papers (continued):
Sharing a sentence is not in itself a finding about the gene and the disease.
Parkinson disease (continued). "PINK1 (PARK6) and PARKIN (PARK2) are causal genes of recessive familial Parkinson's disease." (PMID 31110043, 2019). "The mechanism of mitophagy has been attributed to a number of key molecules, particularly phosphatase and tensin homologue deleted on chromosome 10- (PTEN-) induced putative kinase 1 (PINK1) and Parkin which were identified in models of Parkinson's disease (PD)." (PMID 31057691, 2019). "However, causative evidence for a role of MFN2-dependent mitophagy via PINK1/Parkin in Parkinson’s disease is still missing." (PMID 31156446, 2019). "Interestingly, relationships between mitochondrial dynamics and pathogenesis have gained intense interest following the discovery that two Parkinson’s disease genes, PINK1 and Parkin, also regulate mitophagy." (PMID 29971063, 2018). "Moreover, the decrease in PINK1 activity was described in many pathological conditions, for example, in cells of patients with Parkinson’s disease." (PMID 30360430, 2018). "In fact, so far only very limited animal model work has focused on the swallowing dysfunction component of Parkinson's disease, including studies on a single genetic variant, the Pink1 rat, and some work on chewing in nonhuman primate models." (PMID 29713446, 2018). "Work on the Pink1 rat has indicated that oropharyngeal dysfunction in Parkinson's disease may appear as an early onset sign; thus, by the time it is diagnosed in patients, dysphagia may be well advanced." (PMID 29713446, 2018). "Park2, Park7 and Pink1 stand out among Parkinson’s disease-specific genes downregulated by both treatments, since they are involved in biological processes characteristic of this disease, like dopamine uptake and neurotransmission, autophagy and degradation of mitochondria." (PMID 30382133, 2018). "Given that mutations in PINK1 and VCP are known to cause Parkinson’s disease (PD) and frontotemporal dementia (FTD), conditions affecting primarily neurons, the discovery that they act in a common pathway to support dendritic arborization has important implications for neuronal health and disease." (PMID 30783609, 2018). "Induced neurons from patients with mutations in the PTEN-induced putative kinase 1 (PINK1) pathway, a genetic risk factor for Parkinson's disease, show reduction of downstream targets of this pathway which are involved in regulation of mitochondrial quality control." (PMID 29479303, 2018). "The Parkinson's disease protein PINK1 is regarded as a master regulator of mitophagy." (PMID 29337137, 2018). "Mutations in PARK2 (Parkin) and PARK6 (PINK1) have been independently linked to familial cases of Parkinson's disease, associating defects in mitophagy with the degeneration of dopaminergic neurons, a major feature of Parkinson's disease." (PMID 29593482, 2018). "Thus, our results identify a novel role of PINK1 modulating the levels of LRRK2 in Parkinson’s disease fibroblasts and neurons, suggest a convergent pathway for these PARK genes, and broaden the role of LRRK2 in the pathogenesis of Parkinson’s disease." (PMID 27975167, 2018). "Individuals possessing homozygous or compound-heterozygous mutations for PINK1 exhibit mood and cognitive dysfunction similar to sporadic and PDD/LBD and are at increased risk for early onset Parkinson’s disease." (PMID 30740041, 2018). "Genetic or pharmacological inhibition of USP14 in vivo corrected mitochondrial dysfunction and locomotion behaviour of PINK1/Parkin mutant Drosophila model of Parkinson's disease, an age‐related progressive neurodegenerative disorder that is correlated with diminished mitochondrial quality control." (PMID 30249595, 2018). "DJ-1 could also be connected with two other Parkinson disease-related genes; Parkin and Pten-induced putative kinase 1 (PINK1) to form the E3 ligase complex, thereby promoting the degradation of unfolded proteins and Parkinsonism." (PMID 28224045, 2017).
Parkinson disease (continued). "To date, it remains unknown whether perturbation of PINK1 and Parkin leads to defects in mitochondrial quality control in Parkinson's derived cells or tissues." (PMID 28408429, 2017). "Understanding why PINK1 has this effect and how to prevent it could be helpful in treating Parkinson’s disease." (PMID 28980524, 2017). "Consequently, for a deeper understanding of the subtle early consequences of Pink1-ablation, we focused the studies of histology and ceramides on the brainstem and olfactory bulb, where Parkinson’s disease starts." (PMID 28768533, 2017). "Furthermore, we demonstrated the recoding of a nonsense mutation in PINK1 to a level sufficient to rescue the mitophagy phenotype that links dysfunctional PINK1 to the etiology of Parkinson’s disease." (PMID 28098820, 2017). "Considering that PINK1 and Parkin have important roles in selective autophagic elimination of the damaged mitochondria in Parkinson’s disease, and that Parkin, a ubiquitin E3 ligase, can be recruited by PINK1 onto impaired mitochondria, presumably for ubiquitinating mitochondrial surface proteins." (PMID 27551434, 2016). "Since PINK1 is thought to play an important role in protecting nerve cells from parkinsonism by inhibiting caspase 3 action, we further investigated if the increase in the activated caspase 3 is associated with a reduction of PINK1 expression in hypoxic and MPP+ conditions." (PMID 27517901, 2016). "We also assayed the sensitivity of ONS cells from patients with monogenic forms of Parkinson’s disease, LRRK2 and PINK-1 mutations, in particular (percentage change at 24 hours = -0.71%, 48 hours = -6.94%, 72 hours = -7.84% 96 hours = -11.67% and 120 hours = -11.89%)." (PMID 27123847, 2016). "Finally, the added value of the Parkinson’s disease ontology is demonstrated by ontology-driven modeling of PINK1 and re-annotation of gene expression datasets relevant to Parkinson’s disease." (PMID 26395080, 2015). "Therefore, the dysfunction of PINK1 and Parkin in patients with Parkinson’s disease results in the impairment of mitophagy, which is regulated by NDP52 and OPTN." (PMID 26569220, 2015). "Since mitochondrial dysfunction and oxidative stress are features of Parkinson’s disease (PD), studying the functions of PINK1, parkin, and DJ-1 may lead to insights about the pathogenesis of sporadic Parkinson’s disease." (PMID 26464968, 2015). "Mutations in PINK1 [PTEN (phosphatase and tensin homologue deleted on chromosome 10)-induced putative kinase 1] and Parkin are associated with early-onset autosomal-recessive PD (Parkinson's disease)." (PMID 24660806, 2014). "Oxidative stress is believed to play an important role in the pathogenesis of PD, with the parkinsonism-linked genes PARK2, PINK1, and DJ1 being associated with mitochondrial dysfunction and increased reactive oxygen species-linked cellular effects (reviewed in Ref." (PMID 24942733, 2014). "The mitochondrial kinase PINK1 and the ubiquitin ligase Parkin are participating in quality control after CCCP- or ROS-induced mitochondrial damage, and their dysfunction is associated with the development and progression of Parkinson's disease." (PMID 24751806, 2014). "The PINK1 gene has been heavily studied in the contest of Parkinson's disease." (PMID 25147748, 2014). "While most cases of Parkinson's disease have no known genetic cause, mutations in either of two genes—PINK1 or parkin—are known to lead to the disease." (PMID 24898855, 2014). "Iron chelation‐induced mitophagy requires that cells undergo glycolysis, but does not require PINK1 stabilization or Parkin activation, and occurs in primary human fibroblasts as well as those isolated from a Parkinson's patient with Parkin mutations." (PMID 24176932, 2013). "PINK1 and PARKIN are causal genes for hereditary Parkinsonism." (PMID 23751051, 2013).
Parkinson disease (continued). "The PTEN-induced putative kinase 1 (PINK1) and the E3-ubiquitin ligase Parkin, both associated with familial form of Parkinson disease (PD), were the first molecules to be related to mitochondrial integrity maintenance in flies and then to mitophagy in mammals." (PMID 24710422, 2012). "For example, accumulation of a causal gene product of Parkinson's disease, PTEN-induced mitochondrial protein kinase 1 (PINK1) on depolarized mitochondria facilitates recruitment of cytoplasmic Parkin, an E3 ubiquitin ligase, to mitochondria to initiate mitophagy." (PMID 22536251, 2012). "A key issue with this is whether administration of PINK1 inhibitors to human cancer patients could have the potential to induce Parkinson's disease." (PMID 22645651, 2011). "Mutations in parkin, PINK1 and DJ-1 cause of recessive Parkinsonism, with a variable pathology often lacking the characteristic Lewy bodies (LBs) in the surviving neurons." (PMID 21244648, 2011). "Mutations in α-synuclein, DJ-1, PINK-1 and Parkin as well as toxins like 6-hydroxydopamine (6-OHDA), rotenone, paraquat and 1-methyl-4-phenyl 1,2,3,6 tetrahyrdopyridine (MPTP) lead to parkinsonism/PD suggesting that degeneration involves a complex and multifaceted pathway." (PMID 22016808, 2011). "The main goal of this work was to describe two MJD patients displaying the parkinsonian triad (tremor, bradykinesia and rigidity), namely on what concerns genetic variation in Parkinson's disease (PD) associated loci (PARK2, LRRK2, PINK1, DJ-1, SNCA, MAPT, APOE, and mtDNA tRNAGln T4336C)." (PMID 22023810, 2011). "The effects of S6K on animal lifespan and PINK1 mutant phenotypes can both be explained by the energy metabolism hypothesis and they offer a tantalizing link between aging and the pathogenesis of Parkinson's disease." (PMID 21151574, 2010). "It will be important to determine whether NCS-1 serves to regulate Pink1 function, either within mitochondria or other cellular compartments, and whether the NCS-1/Pink1 interaction contributes to the etiology of Parkinson's disease." (PMID 19320994, 2009). "The question arises as to whether the PINK1 gene is also a candidate gene for late-onset forms of Parkinson's disease, similar to the suggested role of the Parkin gene." (PMID 16354302, 2005). "Loss-of-function mutations in the PINK1 and PRKN genes are the most common cause of early-onset Parkinson disease (PD)." (PMID 40624741, 2025). "In the context of Parkinson’s disease treatment, inhibiting USP30 increases translocase of outer mitochondrial membrane 20 (TOM20) ubiquitination and promotes mitophagy, offering a potential therapeutic strategy for Parkinson’s disease caused by PTEN-induced kinase 1 (PINK1) or Parkin mutations." (PMID 40918504, 2025). "In addition to PARK6 (encoding PINK1) and PARK2 (encoding Parkin), other genes associated with Parkinson’s disease, such as PARK7 (encoding the DJ-1 protein) and PARK8 (encoding the LRRK2 protein), are also thought to be mutated in patients with Parkinson’s disease." (PMID 40463912, 2025). "Interestingly, the lack of Miro has been shown to counteract the effects of PINK1 mutations linked to Parkinson's disease in Drosophila and helps remove damaged mitochondria in HeLa cells." (PMID 40406921, 2025). "Indeed, three well validated autosomal dominant genes (SNCA, LRRK2, and VPS35) and three well validated autosomal recessive genes PRKN, PINK1, and DJ1 are known to cause Parkinson’s disease, inducing defects in mitochondria, axonal transport, and the dopaminergic system." (PMID 41302176, 2025).
Parkinson disease (continued). "PINK1 (PTEN-induced putative kinase 1) and Parkin (encoded by PARK2), encoding a mitochondrially targeted kinase and E3 ubiquitin ligase, respectively, have been implicated in Parkinson’s disease, with mutations in these genes causing autosomal recessive parkinsonism." (PMID 38397070, 2024). "Additionally, 3-5% of cases can be attributed to monogenic inheritance associated with known Parkinson's disease-related genes, such as SNCA, LRRK2, VPS35, PRKN, PINK1, DJ-1, and GBA, while genetic variants collectively account for 16-36% of the non-monogenic heritable risk." (PMID 38879763, 2024). "PD-related genes have been discovered, for example, α-synuclein, Parkin, PINK1 (phosphatase and tensin homologue-induced putative kinase 1), LRRK2 (leucine-rich repeat kinase 2), and DJ-1 (also known as Parkinson disease protein 7 [PARK7])." (PMID 38841098, 2024). "Recent studies have shown that cases of Parkinson’s related to mutations in PINK-1 share features with some non-inherited instances of the disease, suggesting that this approach could potentially benefit many patients." (PMID 39159312, 2024). "PTEN-induced kinase 1 (PINK1) regulates Parkinson's disease, but its role in cancers is unknown." (PMID 36823640, 2023). "PINK1 (PTEN induced kinase 1) and PRKN-mediated mitophagy is an important mitochondrial quality control pathway which selectively degrades damaged mitochondria and is tightly associated with neurodegenerative diseases, including Parkinson disease and amyotrophic lateral sclerosis." (PMID 40395318, 2023). "In addition, BAG2 also interacts with PINK1, a Parkinson's disease-related protein, and directly binds and stabilizes both wild-type PINK1 and the R492X PINK1 mutant by decreasing their ubiquitination, which contributes to the pathogenesis of Parkinson's disease." (PMID 36593950, 2023). "In addition, considering the pivotal role of PINK1 in Parkinson’s disease, it is conceivable that palmatine treatment could also prove advantageous in PD models." (PMID 38003731, 2023). "Synaptic dysfunction and dendritic pathology contribute to the early stages of neurodegeneration, suggesting that reduction in the levels of the cleaved PINK1 during the JEV infection may contribute to the development of Parkinson’s disease-like manifestations in the JE patients." (PMID 35604158, 2022). "In these patients, due to disrupted PINK1 function, mitochondrial quality control is compromised, and accumulation of damaged mitochondria leads to oxidative stress, which inhibits dopamine secretion and neuronal synaptic transmission, resulting in Parkinson’s disease." (PMID 35628458, 2022). "Of note, PINK1 and PRKN are mutated in autosomal recessive Parkinson disease (PD) and their roles in mitophagy indicate the connection between mitophagy and PD, which will be discussed in detail in the following sections." (PMID 34829881, 2021). "In addition to Parkinson’s disease, a previous study reported that 12-week treadmill training also enhanced mitophagy in an Alzheimer’s disease mice model, as evidenced by reductions in the levels of dysfunctional mitochondrial detectors (PINK1 and p62)." (PMID 34440215, 2021). "Psychological distress promotes alterations in brain metabolism and neurochemistry in wild-type (WT) rats in a similar manner as in Parkinsonian rats lacking endogenous PTEN-induced kinase 1 (PINK1), a serine/threonine kinase mutated in a recessive forms of Parkinson’s disease." (PMID 32555260, 2020). "Importantly, fwd overexpression is able to substantially suppress locomotor and mitochondrial phenotypes in Pink1/parkin mutants, suggesting that manipulating phosphoinositides may represent a route to tackling Parkinson’s disease." (PMID 33085661, 2020).
Parkinson disease (continued). "In a Parkinson’s Disease (PD) cohort of very modest sample size compared to contemporary GWAS studies, GenePy successfully identified association with the PINK1 gene but failed to reach significance for five other known genes when looking across the entire distribution of scores." (PMID 31096927, 2019). "Thus, in the present study, we tested the hypothesis that caspase-3 modulates synaptic plasticity at corticostriatal synapses in the phosphatase and tensin homolog (PTEN) induced kinase 1 (PINK1) mouse model of Parkinson’s disease (PD)." (PMID 31336695, 2019). "Therefore, our finding that PINK1 regulates BCAA catabolism may have important implications for patients suffering from Parkinson disease." (PMID 31681280, 2019). "Thus, through the study of Parkinson's disease-related etiopathology, a great deal of information related to the role of PINK1 in the maintenance of cellular homeostasis has been generated and the information has been related to a wide range of age-related dysfunctions." (PMID 30116473, 2018). "Moreover, the T313M mutation of PINK1, an important regulator of mitochondrial trafficking, abolishes its phosphorylation by a protein kinase MARK2, exhibits toxic effects in neurons, and is involved in neurodegeneration in Parkinson’s disease (PD)." (PMID 30244175, 2018). "PTEN-induced putative kinase 1 (PINK1) is a mitochondrial Ser/Thr kinase that was identified as an autosomal recessive gene for familial recessive early-onset Parkinson disease (PD) in 2004." (PMID 29325568, 2018). "Mitochondrial impairment is an important feature of Parkinson disease (PD), in which both familial parkinsonism genes DJ‐1 and PINK1 have a great impact on mitochondrial function." (PMID 30133157, 2018). "It is known that autophagy defects lead to neurodegeneration even in cases where poly-Q protein expansions are not involved; e.g., in the Pink1 and Parkin loss-of-function leading to Parkinson disease, where mitophagy defects are proposed to induce neuronal death." (PMID 25888134, 2015). "Furthermore, mutations in the PTEN induced putative kinase 1 (PINK1) gene have been linked to early-onset familial Parkinson’s disease, while ablation of PTEN in dopaminergic neurons is neuroprotective in mouse models of Parkinson’s disease." (PMID 23029078, 2012). "The strong genetic interaction between PINK1 and Miro raised the interesting possibility that PINK1 might directly regulate mitochondrial transport, the impairment of which might contribute to PINK1-related parkinsonism." (PMID 22396657, 2012). "Experiments aimed to eliminate or over-express selected genes that are altered in Pink1−/− mice will ultimately lead to improved animal models for recessive Parkinsonism and the identification of genes and pathways that could serve as targets for future PD therapy." (PMID 21249202, 2011). "Two of these genes, PINK1 (PARK6, OMIM #605909, Gene ID: 65018) and parkin (PARK2, OMIM #600116, Gene ID: 5071), are associated with early-onset autosomal recessive PD, in which loss-of-function (LOF) of a single gene product results in the clinical manifestation of Parkinsonism." (PMID 21151955, 2010). "In Parkinson's disease, where complex I deficiency is also observed, loss of function of PTEN-induced kinase 1 (PINK1) may contribute to disease pathogenesis by promoting mitophagy, the regulation of which appears tightly linked to oxidative stress and mitochondrial dynamics." (PMID 19640278, 2009). "SIAH1, a member of the same family as SIAH2, has been reported to promote mitophagy through the PINK1-synphilin-1-SIAH1 signaling axis, contributing to the progression of Parkinson’s disease." (PMID 40004017, 2025). "The mutants included in this study are ‘classical’ Parkinson disease genes, like LRRK2 and PINK1, and Parkinsonism genes that affect vesicle trafficking processes, including SYNJ1, DNAJC6/Aux. and RAB39B." (PMID 40178224, 2025).